MRPS11P1 (mitochondrial ribosomal protein S11 pseudogene 1)
Synonyms: dJ746H2.1
Gene: Processed pseudogene on chromosome 20 (20,854,121 to 20,854,642, reverse strand). Ensembl gene ENSG00000225803.
Diseases named in the same sentence as MRPS11P1 in open-access papers:
MRPS11P1 is named in the same sentence as 1 disease in open-access papers, as found by Europe PMC text mining. Sharing a sentence is not in itself a finding about the gene and the disease.
MRPS11P1 shares sentences with these, for which no sentence is quoted: diabetes (1 paper).